BRAF (B-Raf proto-oncogene, serine/threonine kinase)
Diseases named in the same sentence as BRAF in open-access papers (continued):
Sharing a sentence is not in itself a finding about the gene and the disease.
cancer (continued). "Notably, as opposed to standard chemotherapy, a non-negligible percentage of BRAF-mutated cancer patients are benefitting from BRAF and/or MEK inhibitors and/or immunotherapy (anti-CTLA-4, -PD-1, -PD-L1) in terms of OS and tolerable toxicity." (PMID 33260892, 2020). "Thus far, high-throughput resequencing efforts worldwide aimed at identifying unknown somatic mutations in human cancer have already revealed that yet uncharacterized mutations in KRAS, NRAS, BRAF, PIK3CA, PTEN and other cancer genes are highly prevalent." (PMID 32620824, 2020). "While the majority of Class 1 (RAF dependent) MAP2K1 mutations are associated with co-mutation in BRAF, NRAS, or NF1, only a small proportion of class 2 (RAF regulated) cases and no class 3 (RAF regulated) cases share these co-mutations in a limited pan-cancer analysis." (PMID 32483240, 2020). "However, this phenomenon was only observed in KRAS and BRAF mutant cancer cells." (PMID 31096937, 2019). "In CM, mutation of BRAF is not sufficient for full transformation and it is highly likely that experimental tumorigenesis using xenografts with transgene overexpression in mice does not underlie the same restrictions as natural cancer evolution in humans." (PMID 31671564, 2019). "Additionally, exoDNAs contain similar mutations, such as BRAF (V600E) and mutated epidermal growth factor receptor (EGFR), as the cancer cell lines from which they originated, suggesting the potential role of exoDNAs as alternative biomarkers in the detection and diagnosis of cancers." (PMID 31078138, 2019). "This suggests that, at least in some cases, rare BRAF mutations may confer a less proliferative advantage to cancer cells as compared to other mutations with a negative prognostic impact." (PMID 31661924, 2019). "As with all current targeted cancer therapeutics, MEKi efficacy is limited by innate and acquired resistance and we have contributed to the understanding of both modes of MEKi resistance in colorectal cancer (CRC) cells, where BRAF and KRAS mutations are common oncogenic drivers." (PMID 35582726, 2019). "Interestingly, PTEN loss is associated with resistance to MEK inhibitors in a variety of cancers, and in fact may be a common mechanism for conferring resistance to other therapies such as PI3Kβ and BRAF inhibitors and immunotherapy." (PMID 31645898, 2019). "The absence of the clinically relevant mutations in KRAS and BRAF in MBC02 suggests that cancer pathogenesis may have been driven by some other mechanism." (PMID 30828563, 2019). "Furthermore, while BRAF inhibitors are effective in blocking growth of cancer cells driven by the BRAF-V600E mutation, BRAF inhibition paradoxically activates MAPK signaling in KRAS mutant tumors through inducing increased dimerization of BRAF with RAS." (PMID 31681559, 2019). "In addition, PIK3CA or BRAF mutations were observed in seven cancer subjects and no non-cancer subjects." (PMID 31711466, 2019). "Since we observed differential expression of oncogenic BRAF in cancer cells with different cell states, we hypothesized that expression of oncogenic BRAF may influence the state of PA cancer cells by modulating one or more of the gene programme identified above." (PMID 31427603, 2019). "In summary, we have identified dabrafenib as a potent inhibitor of NEK9 and CDK16, and our studies suggest that inhibition of these kinases may have activity against cancers that do not harbor BRAF mutations." (PMID 29112787, 2018). "SSAs may methylate an epigenetic target other than MLH1 and result in BRAF mutant/MSS cancers." (PMID 30598662, 2018). "More moderate missense APC mutations occur in BRAF mutant/MSI cancers which may influence the Wnt signal, and it was found that 87% of BRAF mutant/MSI cancers mutate RNF43 which is a negative regulator of the Wnt signal." (PMID 30598662, 2018).
cancer (continued). "The class 1 BRAF V600E mutation and also class 2 mutations allow for constitutive activation of the pathway; therefore, a concurrent KRAS mutation is redundant which is indicated by the mutual exclusivity of these two mutation types occurring in a single cancer." (PMID 30598662, 2018). "However, Malesci and coworkers reported that MSS cancers presenting with the phenotype of multiple advanced lesions account for the vast majority of sCRCs and do not have BRAF mutations." (PMID 29652830, 2018). "However, that there is a precedent for functional and therapeutically actionable EGFR, MET, and BRAF kinase domain duplications in other cancers is suggestive that a similar mechanism may be applicable to the observed RET kinase duplications in breast cancer." (PMID 30446652, 2018). "Accumulating evidence shows that genetic mutations in cancer-driver genes, tumor suppressors, and amplified oncogenes are linked to specific alterations in metabolic pathways in cancer cells, involving proteins such as isocitrate dehydrogenase (IDH), fumarate hydratase (FH), MYC, K-RAS and BRAF." (PMID 30369878, 2018). "Furthermore, the non-invasive follow-up strategy included only the BRAF V600E mutation which is clinically relevant to only a subset of patients and complementary NGS analysis covering other cancer hotspot genes should be considered for early discovery of driver and resistance alterations." (PMID 30220966, 2018). "Cancer cells may switch between these RAF variants, upregulating ARAF or CRAF when BRAF is blocked." (PMID 29100459, 2017). "Thus, MEK and mTOR co-targeting may represent a successful, generalized targeting strategy against diverse BRAF-fusions that warrants careful testing in PLGGs as well as other pediatric and adult cancers where additional BRAF-fusions are being discovered." (PMID 29156677, 2017). "However, the potency of immune checkpoint therapies has ushered in a new era of cancer treatment by offering the possibility of combining these drugs with conventional cancer treatments such as radiation, chemotherapy, and targeted molecular therapy (e.g., BRAF/MEK inhibitors)." (PMID 29276510, 2017). "Moreover, a few reports have focused on the relationship between BRAF mutations and some miRNA alterations in other cancers, although their miRNA expression profiles were not similar." (PMID 29115941, 2017). "While weighing the treatment options for these two cancers, although our initial thoughts were to focus on the more aggressive melanoma (BRAF and NRAS wild type), we were motivated to design a therapy regimen that could yield efficacious responses against both cancers." (PMID 27099755, 2016). "The BRAF mutation is known to be mutually exclusive with KRAS and/or NRAS mutations in other cancers; however, in our study, mutations in BRAF did not appear to be exclusive to either the KRAS or NRAS mutation because mutations in KRAS, NRAS, and BRAF were all found in the same patient (patient #1)." (PMID 27634910, 2016). "For example, a recent screen for genes increasing the efficacy of RAF inhibitors in cancer cells harboring BRAF-V600E mutations identified YAP as a key to drug resistance, and combined YAP and RAF or MEK inhibition was found to be synthetically lethal for BRAF and RAS mutant tumors." (PMID 27144834, 2016). "BRAF mutant/MSS cancers also commonly showed deletion of the RNF43 locus at 17q22, which may contribute to gene silencing and compensate for the lower RNF43 / ZNRF3 mutation rate in this cancer subgroup." (PMID 27661107, 2016). "Similarly, BRAF inhibitor decreased pERK in cells with BRAFV600E mutations, but as expected, caused a paradoxical increase in pERK in the BRAFWT cancer cells." (PMID 26943572, 2016).
cancer (continued). "This inhibitor is deemed tolerable, with an acceptable margin of safety when administered using intermittent dosing regimens, demonstrating that TGFBR1 inhibitors are suitable for clinical use and may provide new opportunities for therapy of BRAF-inhibitor resistant cancer." (PMID 27835901, 2016). "Therefore, our unique fusion is expected to retain all functional domains as the wild-type BRAF and whether it is targetable in cancer remains to be determined." (PMID 25985019, 2015). "BRAF status was associated neither with the cancer relapse nor with the time to relapse." (PMID 26177218, 2015). "These include recognised tests such as RAS, BRAF and EGFR mutation detection, OncotypeDX, Mammaprint and a range of emerging next generation sequencing oncology panels which will further enhance the molecular profiling of tumors and the targeted treatment of cancer patients." (PMID 26317646, 2015). "These human cancer studies showed that BRAF mutational status alone does not predict the therapeutic potential of BRAF inhibition for cancers, suggesting that understanding of molecular networks important for cancer cells is crucial." (PMID 29061943, 2015). "Upregulation of ALDH3B1 in BRAF(+) PTCs may constitute a mechanism of cancer cell survival." (PMID 26625260, 2015). "Furthermore, one patient with an increased BRAF copy number had experienced cancer recurrence." (PMID 25621040, 2015). "Interestingly, one of the BRAF mutated cancers was contiguous to a hyperplastic/serrated area without areas of dysplasia." (PMID 25983749, 2015). "Similarly, the average percentage of methylated reference (PMR) scores which indicates the extent of methylation of a cancer relative to a methylase treated reference sample, was significantly higher in the BRAF mutant compared to the BRAF wild type cohort (27 vs 3; p < 0.0001)." (PMID 25613750, 2015). "Furthermore cross-talk between RAS and BRAF oncogenes with other mutated pathways like PI3K and APC will provide new molecular mechanisms and will assist the design of efficient rational combinatorial anti-cancer protocols for personalised therapy." (PMID 25361007, 2014). "In addition, BRAFV600E mutation has recently been correlated with significantly increased cancer-related mortality, as mortality was 5.3% in patients positive for the BRAF mutation and only 1.1% in those without the mutation." (PMID 24673746, 2014). "In summary, the possibility that in KRAS and BRAF mutant cancer cells differential signalling mechanisms that involve MEK supported the mutual exclusivity of these two mutations, lead to the target-specific cancer therapeutics in the form of monoclonal antibodies against EGF and VEGF receptors." (PMID 25361007, 2014). "The use of specific small molecule inhibitors of mutant BRAF in patients with tumors harboring a BRAF V600 mutation has demonstrated that neither within, nor across, cancer frequency is sufficient to determine the functional significance of inhibiting “driver” mutations." (PMID 25435088, 2014). "The possibility that in KRAS and BRAF mutant cancer cells differential signalling mechanisms that involve MEK, supported the mutual exclusivity of these two mutations, lead to the target-specific cancer therapeutics in the form of monoclonal antibodies against EGFR and VEGF receptors." (PMID 25361007, 2014). "The main question that would need to be ascertained might be whether or not patients who have that tumor type (e.g. BRAF-mutated cancer) benefit from the therapy overall, rather than if there are salutary effects for each histologic subtype or patient." (PMID 25593991, 2014). "As KRAS and BRAF mutations are associated with poor response to anti-EGFR therapy in some cancers, it has been suggested that screening for KRAS and BRAF mutations in RCC may be a promising strategy to identify patients who might respond to EGFR-targeted therapy." (PMID 28326248, 2014).
cancer (continued). "The hierarchical tree of this subset of probes revealed two distinct clusters: Group 1, mostly composed by TAs and MSS cancers with KRAS mutations; and Group 2 with BRAF mutations, which consisted of cancers with MSI and MLH1 methylation (Group 2A), and SSAs without MLH1 methylation (Group 2B)." (PMID 24964857, 2014). "However, BRAF mutations are not specific to serrated tumours, also being found in colonic adenomas and cancers without a serrated morphology." (PMID 23671423, 2013). "In this study we also observed that PIK3CA codon 545 substitutions account for 9.8% of PIK3CA mutations in CRC and, since the carcinoma carrying the PIK3CA p.Glu545Asp mutation did not present mutations in either KRAS or BRAF, it is conceivable that this mutation confers some selective advantage." (PMID 23548132, 2013). "Furthermore, activated Raf can contribute to the epithelial-mesenchymal transition which hallmarks the initiation of metastasis and may help to explain the aggressive nature of the BRAF mutant/MSS cancers." (PMID 23110075, 2012). "However, based on our previous finding of multiple molecular and clinical similarities between the two MSS subgroups, we hypothesised that chromosomal instability would contribute to progression of a substantial proportion of BRAF mutant/MSS cancers." (PMID 23110075, 2012). "As BRAF mutant/MSS cancers have a constitutively active MAPK pathway, loss of the SMAD loci may be redundant and could help to explain the significantly lower rate of deletion found at the 18q region in these compared to BRAF wild type/MSS cancers." (PMID 23110075, 2012). "Additionally, we report on the novel finding of both CIN and CIMP co-occurring in BRAF mutant/MSS cancers, and potentially the combined impact of such may contribute to the detrimental outcome for patients with this cancer type." (PMID 23110075, 2012). "We have previously demonstrated clinical and molecular similarities between MSS cancers with or without a BRAF mutation, and therefore hypothesised that CIN may also be frequent in BRAF mutant/MSS cancers." (PMID 23110075, 2012). "E6201 is a novel MEK1/2 inhibitor which inhibits selected cancer-specific kinases that is currently in clinical trials for solid tumours and, as a result of the data presented herein, is undergoing Phase I expansion in BRAF-mutant malignancies (NCT00794781, ClinicalTrials.gov)." (PMID 23039341, 2012). "Thus mutation at both BRAF and CRAF have been detected in certain cancer patients and other studies have shown that the levels of mutant and WT B-Raf, Raf-1 and RKIP will influence the levels of transformation observed, hence there is a strong basis for the development of Raf inhibitors." (PMID 21422497, 2011). "BACKGROUND: While combination BRAF and MEK inhibitor treatment in BRAFV600E-mutant cancers results in a response, treatment resistance and toxicity are common." (PMID 41501927, 2026). "NST-628 inhibits all RAF isoforms (ARAF, BRAF, CRAF) and works across multiple RAS- and RAF-mutant cancers, including those resistant to existing therapies." (PMID 41514664, 2026). "All three carcinoma populations of different DI showed similar profiles with sCNA, including MYC, GNAS, BRAF amplifications and, as expected, ERBB2 high‐level amplification." (PMID 41144934, 2026). "The carcinoma population had a very high TFx (0.96), with 34 sCNA and regions containing FGFR1, CCND1, GNAS, and BRAF the most amplified." (PMID 41144934, 2026). "Our data provides compelling evidence that peptide-gold nanoparticles, particularly AuNP-p-CPS62, possess potent anti-cancer ability by down-regulating the expression of c-Myc, TERT, and BRAF via blockade of c-Myc/TERT interaction." (PMID 40860184, 2025). "These included some notable oncogenes known to be drivers in the found cancer types, such as PIK3CA in BRCA, BRAF in SKCM, and EGFR in LGG and LUAD, and KRAS across several cancers including PAAD, LUAD and COAD." (PMID 41415395, 2025).
cancer (continued). "While the drugs targeting PD-1 BRAF V600E and RET fusion for pan-cancer treatment is considered as an expansion of the existing drugs for pan-cancer, Vitrakvi® targeting NTRK is a drug truly developed for pan-cancer treatment." (PMID 41294857, 2025). "Many cancer patients receive targeted therapies against upstream regulators of Rsk2, such as EGFR, BRAF, or MEK inhibitors." (PMID 40634321, 2025). "This visualization highlights key genes (TIMP3, BRAF, and ITGB1, among the top 10 genes) that participate in multiple cancer-related and metabolic pathways, suggesting potential functional hubs and crosstalk among signaling networks." (PMID 41294900, 2025). "We found that the ratio of infiltrating endothelial cells to cancer cells, a possible marker of vascular invasion, was an independent predictor of progression‐free survival (PFS) in the BRAF+MISSONI cohort (p = 0.033, HR = 1.44, CI = 1.029–2.01)." (PMID 39788558, 2025). "Together, these findings suggest the combined therapy with dual inhibition of BRAF and MEK exerts significant effects on cancer cell metabolism through several possible mechanisms." (PMID 39984334, 2025). "A major breakthrough came with a phase II trial in BRAF V600E-mutant ATC, a highly aggressive and historically treatment-resistant cancer." (PMID 41368991, 2025). "Besides the well-known role of mutations in members of the MAPK pathways, such as BRAF and NRAS, an increasing number of studies have linked gene polymorphism and genetic variants to the members of the PI3K/AKT signaling pathway as susceptibility for cancer development." (PMID 40075679, 2025). "Currently, six pan-cancer biomarkers—NTRK, BRAF V600E, RET, HER2-positive, MSI-high, and TMB-high—along with nine molecularly targeted therapies have expanded treatment options across diverse malignancies." (PMID 40576713, 2025). "Not only does PA make RAF inhibitors ineffective for targeting RAS mutant cancers, PA also contributes to off-target effects when RAF inhibitors are used on BRAF V600E mutant cancers." (PMID 40749078, 2025). "Rat sarcoma (RAS) family genes (KRAS, NRAS) and v-raf murine sarcoma viral oncogene homolog B1 (BRAF) play a key role in the epithelial growth factor receptor (EGFR) pathway, an essential pathway for survival of cancer cells." (PMID 40927517, 2025). "Based on our bioinformatics analysis of the BRAF/MEK/PI3K oncogenic signature and numerous lines of evidence that mono-targeted therapies often fail to improve the outcome of cancer patients, including CRC, due to the development of drug resistance." (PMID 41009348, 2025). "Early detection of these mutations is critical for determining optimal treatment strategies, with BRAF inhibitors showing significant advancements in PFS and OS rates among cancer patients." (PMID 40141188, 2025). "Due to the virtually complete loss of GTPase activity, the signal should be chronically transduced, mainly to BRAF and AKT proteins, and this process is thought to translate into the increased proliferation of cancer cells." (PMID 40597785, 2025). "Cancer cells with RET/PTC1 rearrangements rely more on the RAF‐1 pathway for survival and growth than on the BRAF‐ERK pathway, which is typically needed in cells with RAS or BRAF mutations." (PMID 40911853, 2025). "Intracellular signaling pathways such as ALK, BRAF/MEK, and PI3K/AKT/mTOR are essential for the growth and survival of cancer cells." (PMID 40872476, 2025). "This field has driven the development of therapies like HER2-targeted immunotherapy, PI3K inhibitors, BRAF inhibitors, and PARP inhibitors, underscoring its transformative impact on cancer care." (PMID 39943159, 2025).